EGFR (epidermal growth factor receptor)
Diseases named in the same sentence as EGFR in open-access papers (continued):
Sharing a sentence is not in itself a finding about the gene and the disease.
tumor (continued). "In our study, Sigmoid-Offset-Mean decreased from 13.12 ± 47.56 in the EGFR-mutant group to −33.34 ± 45.67 in EGFR-wildtype group, suggesting that tumors in EGFR-mutant group have a smoother tumor boundary." (PMID 33681463, 2021). "Using EGFR vIII-positive xenografts, combination therapy of olaparib and EGFR vIII-targeted CAR T-cells enhanced anti-tumor immunity by reducing MDSC migration and improving CD8+ T-cell infiltration." (PMID 34065010, 2021). "Recently, it has been reported that PKP2 promotes tumor development by enhancing ligand-dependent and independent EGFR dimerization and activation." (PMID 34769306, 2021). "In summary, the tumour volume shrinkage rate after EGFR-TKI treatment in patients with stage IV NSCLC with driver Gene-positive mutations gradually slowed over time and varied in each individual." (PMID 34631535, 2021). "All the activated signalling pathways triggered by HER3 heterodimerization with HER2 or EGFR increase cancer cell proliferation, tumour growth, angiogenesis, invasion, and metastasis 58,59." (PMID 33452359, 2021). "Recent studies have suggested that NSCLCs with uncommon EGFR mutations, including EGFR Ex20ins mutations, tend to be positive for CD8+ tumor infiltrating lymphocytes in approximately 50% to 60% of cases." (PMID 33946594, 2021). "In nude mice bearing A431 xenografts, the 68Ga-EGFR-Nb showed a high tumor uptake as well as high tumor-to-normal tissue ratios." (PMID 34575943, 2021). "Overexpression of EGFR expression in PDAC as well as its precursor lesions has made it a viable target for tumor-targeted imaging and therapy." (PMID 34885196, 2021). "Several lines of evidence developed in our laboratories indicate that cMet plays an important role in tumor-intrinsic resistance to EGFR inhibition." (PMID 32545260, 2020). "Background: circulating tumor DNA (ctDNA) is a source of tumor genetic material for EGFR testing in NSCLC." (PMID 32998450, 2020). "Presentation of these peptides in each of the 60 capsid proteins of recombinant adeno-associated viruses (rAAV) via a genetic based loop insertion enabled targeting of EGFR overexpressing tumor cell lines." (PMID 33333826, 2020). "Conversely, one tumor pair shared missense mutations in three genes (EMSY, SMAD4, and POM121L12) and gene copy number amplification of three genes (SDHA, TERT, and EGFR)." (PMID 33139840, 2020). "In the context of PDT, several approaches for molecular tumor targeting employing nanoconstructs have been used for the photodynamic destruction of tumor cells over-expressing EGFR, HER-2, and TfR receptors." (PMID 32726945, 2020). "EGFR allosteric inhibitors such as EAI045 have the potential to inhibit aggressive tumor growth that harbour EGFR L858R/T790M/C797S in conjunction with cetuximab." (PMID 32666476, 2020). "Tumor PD-L1 expression was evaluated using tumor specimen obtained after the first-line treatment with an EGFR-TKI in five patients, because the tissue specimens obtained before the first-line treatment were not available." (PMID 33255696, 2020). "MIA Paca-2 and SCC-9 nodules were formed with the addition of low-EGFR-expressing T47D or SKOV-3 cells that represent tumor subpopulations which we have shown to evade EGFR-targeted PDT using Cet-PINs." (PMID 32726945, 2020). "RNF113A expression was higher in our clinical cases of pulmonary adenocarcinomas than in tumor-free lung parenchymas, independently of the K-RAS or EGFR mutational status." (PMID 32152280, 2020). "In this context, a previous study showed that over-expression of IFIT1 in OSCC cells promote tumor growth and metastasis by activating EGFR signaling." (PMID 32961854, 2020). "Tumor side also affects the choice of treatment, since left-sided neoplasms shown higher response rates to anti-EGFR treatments." (PMID 32241284, 2020).
tumor (continued). "In some cases, multiple fusion transcripts leading to EGFR C-terminal truncation can be detected in the same tumor sample suggesting possible clonal heterogeneity." (PMID 32466770, 2020). "The tumor mostly originates from the mucosal surface of the epithelial tissues that line the head and neck regions, and therefore, gene such as EGFR which maintain the integrity of the epithelial tissues needs to be investigated." (PMID 33273921, 2020). "In this context, the clinical benefits of EGFR inhibitors have been observed in different types of tumour." (PMID 32823532, 2020). "In the majority of patients, the clinical course of EGFR TKI anti-tumor activity is characterized by an initial period of efficacy, followed by disease recurrence." (PMID 32183160, 2020). "The Western blotting results showed the strong inhibition of the tumor growth signaling pathway of EGFR/Erk/Akt by the T12/P-Lipo." (PMID 32483443, 2020). "We now explore the mechanics of EMT induction during the development of drug resistance for three generations of EGFR-TKIs, focusing on the tumor cells per se." (PMID 33028808, 2020). "Cancer cells from different areas in a tumor mass possessed different EGFR statuses and PD-L1 expression." (PMID 32093629, 2020). "HnRNP A3 and EGFR showed elevated colocalization in tumor sections compared with adjacent normal sections." (PMID 32321917, 2020). "Through binding of EGF to EGFR tumour aggressiveness can increase and enhance cell proliferation, migration and probably metastasis." (PMID 32570802, 2020). "aimed at simultaneously targeting cell proliferation and death pathways in tumor cells using MSCs armed with a bi-functional molecule comprised of a nanobody targeting the EGFR (Enb) and TRAIL." (PMID 33117154, 2020). "To further validate the molecular mechanism of MYLK-AS1 in HCC, we detected downstream molecules of EGFR/HER2-ERK signaling pathway of tumor tissues from the xenotransplantation model." (PMID 32398965, 2020). "EGFR, observed in approximately 57% of GBMs, acts as a major driver of tumor invasion, progression, and angiogenesis." (PMID 32957084, 2020). "High tumour EGFR protein expression shows promise to identify those who will benefit from erlotinib." (PMID 32958821, 2020). "High expression or aberrant activation of epidermal growth factor receptor (EGFR) is related to tumor progression and therapy resistance across cancer types, including non-small cell lung cancer (NSCLC)." (PMID 32694521, 2020). "In conclusion, non-coding RNA, tumor microenvironment and exosomes are closely related to EGFR monoclonal antibody resistance." (PMID 32793499, 2020). "This agent enables tumor-specific EGFR-targeting as well as subsequent delivery of the cytotoxic payload independent of EGFR dependency." (PMID 33256808, 2020). "Specifically, stimulation of tumor cells with recombinant TGF-beta limited the efficacy of anti-EGFR agents erlotinib and cetuximab in vitro, and blocking TGF-beta in vivo consequently enhances sensitivity to cetuximab in HNC model." (PMID 32028632, 2020). "Some studies focused on tumor EGFR copy number in relation to monoclonal antibody therapies resistance." (PMID 32580435, 2020). "FAM83A is involved in regulating a variety of different tumor-related signaling pathways, including the EGFR, RAS/RAF/MEK/ERK, and PI3K/AKT/mTOR pathways." (PMID 32195172, 2020). "Our data identified α 5-nAChR as an essential mediator for low-dose nicotine-dependent LAC progression possibly through signaling crosstalk with EGFR, supporting the involvement of environmental smoke in tumor progression in LAC patients." (PMID 32957649, 2020). "A closer look between accumulation of [89Zr]Zr-cetuximab within the tumor and total EGFR/GAPDH ratios revealed a strong positive correlation (r = 0.9461, p = 0.0011)." (PMID 32295603, 2020). "A rare EGFR exon 2–28 duplication was discovered in both preimmunotherapy and postimmunotherapy tumor tissues." (PMID 32581041, 2020).
tumor (continued). "Tumor cells with high expression of EGFR are often accompanied by a significant increase in the level of pro-angiogenic factors, resulting in increased angiogenesis." (PMID 32793499, 2020). "Single cell analysis of EGFR amplification, for example, shows that multiple EGFR amplifications frequently coexist within the same tumor." (PMID 32117316, 2020). "They incorporated a nanobody targeting EGFR as the targeting module, which effectively retargeted UniCAR T cells to EGFR+ tumor cells and mediated specific cell lysis in vitro and in vivo." (PMID 33007850, 2020). "Preclinical models of HNSCC described c-Src kinase involvement in tumor resistance to EGFR inhibitors." (PMID 32517369, 2020). "We demonstrated that CD99 activation regulates actin cytoskeleton dynamics through PTPN12/FAK/Rho/Rac axis, thereby suppressing EGFR activation and relevant tumor growth." (PMID 33050232, 2020). "An end-to-end pipeline including automatic tumor identification, localization, and EGFR status prediction can be developed." (PMID 33643902, 2020). "We herein explored the molecular mechanism underlying the suppression of ligand-induced EGFR dimerization by CD99 agonists and its relevance to tumor growth in vivo." (PMID 33050232, 2020). "For instance, EGFR inhibitor AG-490 can effectively suppress tumor cell proliferation by limiting the expression of cyclin D1." (PMID 33392203, 2020). "It is also suggested that there are fundamental changes in EGFR signalling that take place during primary tumour invasion, dissemination and the ultimate metastasis of BC cells." (PMID 32632202, 2020). "On the other hand, the expressions of KRAS and EGFR in primary tumor tissues were shown to be significantly higher than those in adjacent normal tissues (p < 0.001)." (PMID 33552955, 2020). "As both tumor cells and healthy squamous epithelium tissue scored high for EGFR, superficial tumors with mostly superficial margins resulted in a relatively low TBS." (PMID 32516897, 2020). "Frequently these modalities are supplemented with concurrent platinum-based chemotherapy or with the EGFR inhibitor cetuximab as many tumours overexpress EGFR." (PMID 33322840, 2020). "EGFR expression was observed in both epithelial cells and surrounding tumor stroma, and VEGF-A in the cell cytoplasm and surrounding stroma." (PMID 32545676, 2020). "We also report on an independent screen aimed to identify genes whose depletion suppressed formation of neoplastic tumors in an existing EGFR-dependent neoplasia model." (PMID 32737065, 2020). "In this study, we identified that the expression levels of β-catenin and RAS were highly increased alongside accumulated EGFR in patient tumor tissues, and their expression levels were correlated in these samples." (PMID 32457491, 2020). "FGFR2, VEGFR2, CSF1R, and EGFR are tyrosine kinases that are constitutively activated in cancer cells to promote tumor progression and angiogenesis." (PMID 33488754, 2020). "EGFR and its respective ligands are overexpressed in various tumours, and this overexpression is correlated with poor prognosis in certain cancers." (PMID 33203961, 2020). "Although the results must be verified further, evaluation of tumor PD-L1 expression as a biomarker in patients with EGFR-mutant NSCLC is expected in the future." (PMID 33255696, 2020). "Cytogenetic study of the tumor cells confirmed GBM IDH1 wild type with TERT mutation and EGFR amplification." (PMID 33391387, 2020). "In this context, it is interesting to note that tumour cells that responded to EGFR-inhibition by growth retardation, promoted complement activation that led to ERK-activation." (PMID 32054454, 2020). "In line with this, infection with the earlier introduced VVs encoding antibodies that target VEGF and EGFR (GLV-1h44), or VEGF and FAP (GLV-1h446) diminished angiogenesis and tumor cell proliferation in human prostate tumor xenografts." (PMID 33167307, 2020).
tumor (continued). "Additional genetic testing revealed the patient was negative for ALK fluorescence in situ hybridization, ROS1, BRAF, and EGFR and PD-L1 22C3 IHC with Tumor Proportion Score (TPS) of <1%." (PMID 33101670, 2020). "The results of circulating tumor DNA assays showed that other than HER2 amplification, novel EGFR-ZNF880 fusion and EGFR E114K mutations developed." (PMID 33371069, 2020). "The results demonstrated increased cell proliferation within the tumor spheroids in the presence of CAFs, correlating with increased expression of EGFR." (PMID 33353547, 2020). "Four months of EGFR-TKI treatment with gefitinib led to decreased tumor size and normalization of serum CEA levels." (PMID 32034239, 2020). "Here, we present a combinatory approach with an EpCAM-directed bispecific antibody retargeting T cells via CD3 to tumor cells and EGFR-directed antibody-fusion proteins with costimulatory ligands of the B7 and TNF superfamily." (PMID 32504247, 2020). "Minicell delivery is achieved through a combination of passive accumulation via the leaky vasculature of the tumor and specific targeting using antibodies to a cell-surface antigen (EGFR) in the tumor." (PMID 32117755, 2020). "Here we show that EGFR/Ras signalling in tumour cells induces the production of CCL20 in a variety of types of cancers." (PMID 32601464, 2020). "By utilizing the tyrosine kinase inhibitors (e.g., gefitinib and erlotinib) or monoclonal antibodies (e.g., cetuximab and trastuzumab), they can inhibit the activities of EGFR/ERBB2 to effectively suppress the tumor cell growth." (PMID 33287876, 2020). "Genomic landscape studies have indicated that activation of the tumor-driving K-RAS/EGFR pathway is highly prevalent in high-grade, locally advanced, relapsed, and chemo-refractory TNBC." (PMID 32846967, 2020). "MMPs contribute to tumor cell proliferation through release of insulin-like growth factors (IGFs) and epidermal growth factor receptor (EGFR) that promote proliferation." (PMID 33520928, 2020). "Despite the promising emergence of circulating tumoral DNA testing, this case report emphasizes the importance of rebiopsy of a progressive epidermal growth factor receptor–mutant tumor." (PMID 32762742, 2020). "To determine the anti-tumor mechanisms of Formo, we first examined the effect of Formo on EGFR signaling." (PMID 32276600, 2020). "Coherent MT dynamics induced by neighboring MΦ were disrupted by drugs targeting epidermal growth factor (EGF) receptor (EGFR) on tumor cells, and MΦ polarization via interleukin 10 receptor, IL10R." (PMID 32665556, 2020). "Another calcium effector, the calcium-activated chloride channel TMEM16A plays a major role in activating EGFR, and this property is exploited by several tumor types." (PMID 32575848, 2020). "EGFR is an excellent target, as it is commonly overexpressed and/or altered in tumor, leading to abnormal cell proliferation and activation of prosurvival pathways." (PMID 33117154, 2020). "Gold nanoparticles coupled to 5FU and anti-EGFR antibody have significantly affected the viability of HT-29 tumor cells capable of inducing apoptosis and necrosis in a time-dependent fashion." (PMID 31947551, 2020). "E.g., patient tumor T16 displayed intratumor genetic heterogeneity, where differences in gene amplicons for EGFR and MDM2 were detected in different tissue fragments dissected from the tumor core." (PMID 33009951, 2020). "Tumor-expressing molecules like the epidermal growth factor receptor (EGFR) can be a suitable target for cancer therapy." (PMID 32421739, 2020). "In the post hoc analysis, EGFR protein expression was evaluated in 61 patients (48.0%) from whom there were sufficient pretreatment tumor tissues for immunohistochemistry, including 32 (50%) from the RT plus icotinib group and 29 (46%) from the RT group." (PMID 33026449, 2020). "In deciding between the use of anti-VEGF or an anti-EGFR, the sidedness of the primary tumor needs to be considered." (PMID 33256170, 2020).
tumor (continued). "To understand the mechanism of in utero exposure to BPA-associated tumor promotion in MMTV-erbB2 mice, we examined signaling in the ER and EGFR/erbB2 pathways in premalignant mammary tissues (PND 70) from mice with different in utero treatments." (PMID 32353937, 2020). "In this review, we will discuss how the transfer of EGFR and EGFR ligands by EVs in cancer can promote metastases, the formation of new tumour blood vessels and decrease the anti-tumour activity of immune cells." (PMID 33143170, 2020). "Logically, co-expression of an EGFR RNAi in RasV12 clones strongly decreases invasive properties of developed tumour, confirming the role of EGFR in RasV12-driven tumourigenesis." (PMID 32385236, 2020). "EGFR signalling on hepatocytes was demonstrated to enhance intrinsic DNA damage repair and chronic inflammatory signalling in obese mice via IL-1β and TNFα abrogates this tumour suppressing effect of EGFR." (PMID 32698506, 2020). "POI was significantly correlated with tumour size, stage, 3-year survival, EGFR, HIF-1α, periostin, and MMP-9 (p < 0.05)." (PMID 33123565, 2020). "Discordant EGFR status and PD-L1 expression suggested that a tumor mass harbored genetic aberration." (PMID 32093629, 2020). "Our results showed that PLAG effectively inhibits tumor metastasis by blocking EGFR transactivation via prompt PAR2 degradation." (PMID 32121107, 2020). "Co-culture of A549 EVs with human THP-1 monocytes and murine RAW264.7 macrophages dramatically increased EGFR levels in these immune cells, suggesting translocation of tumour-derived EV EGFR." (PMID 33143170, 2020). "Triple-negative tumours with overexpression of EGFR exhibit constitutive activation of EGFR-dependent signalling pathways, especially the PI3K/AKT/mTOR pathway." (PMID 32286420, 2020). "Further experiments suggested the IL-1α/IL-1R/MYD88/IL-6 pathway as responsible for the reduced anti-tumor efficacy of erlotinib and other EGFR inhibitors." (PMID 33115415, 2020). "Epidermal growth factor receptor (EGFR) overexpression is observed in more than 80% of NPC, and is associated with tumor invasiveness, treatment resistance, and poor prognosis." (PMID 33008416, 2020). "When the anti-EGFR mAb is interrupted, the selecting pressure on the sensitive clones is withdrawn and the tumor can regain sensitivity to the targeted therapy." (PMID 32825275, 2020). "The RADIANT trial enrolled patients with fully resected stage IB to IIIA NSCLC and confirmed tumor EGFR expression by immunohistochemistry (IHC) or fluorescent in situ hybridization (FISH)." (PMID 32878298, 2020). "Based on our study, EGFR seems a more suitable candidate for molecular imaging in PSCC based on the higher tumor-to-background ratio compared to VEGF." (PMID 32942549, 2020). "The tests included recommended techniques currently used in clinical practice for identifying mutations in EGFR (e.g. RT-PCR), and ALK and ROS1 (e.g. FISH), to the single test using NGS for tumor tissue samples." (PMID 32928143, 2020). "In EGFR‐targeted tumor imaging, the positive tumors were clearly located with a high SNR (up to 7.15)." (PMID 32191387, 2020). "NT increases tumour sphere formation and regulates stem-like traits via an EGFR-dependent increase of interleukin-8 (IL-8) secretion." (PMID 32336282, 2020). "Proof-of-concept was shown for tumor-specific protease-activation of a prodrug that can reduce on-target toxicity for an EGFR-targeted antibody with N-terminally fused blocking peptides and a protease cleavable linker." (PMID 32581215, 2020). "FPR1 and EGFR by their respective agonists to mediate tumor cell migration, growth and formation of cell colonies." (PMID 32038501, 2020).